EXOC3L4 (exocyst complex component 3 like 4)
Synonyms: C14orf73
Tractability: PROTAC: ubiquitination databases record sites on it; its protein half-life has been measured.
Gene: Protein-coding gene on chromosome 14 (103,094,538 to 103,110,570, forward strand). Ensembl gene ENSG00000205436.
Gene Ontology:
Molecular function: SNARE binding
Biological process: exocyst localization; exocytosis
Cellular component: exocyst
Genetic constraint (gnomAD): Loss-of-function variants: 63 observed, 50.71 expected, observed/expected ratio (o/e) 1.24, 90% interval 1.01 to 1.53. The synonymous counts are far from expectation, so gnomAD's model fits this gene poorly and the ratio says little. Missense variants: 1,084 observed, 843.45 expected, observed/expected ratio (o/e) 1.29, 90% interval 1.22 to 1.35. Synonymous variants: 501 observed, 374.05 expected, observed/expected ratio (o/e) 1.34, 90% interval 1.24 to 1.44.
Homologues: Orthologues: chimpanzee EXOC3L4 (99% identical), macaque EXOC3L4 (93% identical), dog EXOC3L4 (76% identical), rat Exoc3l4 (73% identical), mouse Exoc3l4 (72% identical), pig EXOC3L4 (69% identical), guinea pig EXOC3L4 (62% identical), rabbit EXOC3L4 (60% identical), tropical clawed frog exoc3l4 (27% identical), zebrafish exoc3l4 (23% identical), zebrafish si:dkey-45k15.1 (18% identical). Paralogues in human: EXOC3L2 (25% identical), TNFAIP2 (21% identical), EXOC3L1 (20% identical), EXOC3 (19% identical).
Diseases named in the same sentence as EXOC3L4 in open-access papers:
EXOC3L4 is named in the same sentence as 5 diseases in open-access papers, as found by Europe PMC text mining. Sharing a sentence is not in itself a finding about the gene and the disease. The quoted sentences say what the papers report.
Alzheimer disease (2 papers, 2018 to 2021). A progressive, neurodegenerative disease characterized by loss of function and death of nerve cells in several areas of the brain leading to loss of cognitive function such as memory and language. "Variants in the splicing regulatory elements of EXOC3L4 were associated with Alzheimer’s disease." (PMID 34182925, 2021).
leukemia (1 paper, 2013). A malignant (clonal) hematologic disorder, involving hematopoietic stem cells and characterized by the presence of primitive or atypical myeloid or lymphoid cells in the bone marrow and the blood. "More interestingly, we also found other genes that had never been associated with leukemias nor with other types of cancer, or had no assigned function such as the Exoc3l4, Hectd2 and AU014947." (PMID 23902727, 2013).
metabolic disorders (1 paper, 2024). "The role of LOC124905962, EXOC3L4, BP11-795H16.2, and BCRP3 in metabolic disorders has not been well-documented yet." (PMID 38997780, 2024).
EXOC3L4 also shares sentences with these, for which no sentence is quoted: cancer (1 paper); infectious disease (1).